CXCL17 (C-X-C motif chemokine ligand 17)
Description:
Chemokine that acts as a chemoattractant for monocytes, macrophages and dendritic cells, and which is involved in immune regulation and lymphocyte trafficking. Activates the C-X-C chemokine receptor GPR25. Plays a key role in lymphocyte homing by activating the receptor GPR25 on lymphocytes, mediating lymphocyte recruitment into the respiratory, upper gastrointestinal, biliary and genito-urinary tracts. Plays a role in angiogenesis and possibly in the development of tumors. Acts as an anti-inflammatory in the stomach. May play a role in the innate defense against infections. [4-Cys CXCL17]: Seems to exhibit much higher chemoattractant potency on monocytes and macrophages than 6-Cys CXCL17.
Synonyms: DMC; VCC1; Dcip1; UNQ473; VCC-1
Tractability: Antibody: UniProt places it where antibodies can reach, with high confidence; UniProt predicts a signal peptide or a membrane-spanning region; its Gene Ontology location is reachable by antibodies, with medium confidence.
Gene: Protein-coding gene on chromosome 19 (42,428,278 to 42,442,996, reverse strand). Ensembl gene ENSG00000189377.
Subcellular location: Secreted
Gene Ontology:
Molecular function: chemoattractant activity; chemokine activity; protein binding
Biological process: cell migration; chemokine-mediated signaling pathway; leukocyte chemotaxis; lymphocyte chemotaxis; monocyte chemotaxis; negative regulation of inflammatory response; positive regulation of cytosolic calcium ion concentration; positive regulation of ERK1 and ERK2 cascade; positive regulation of macrophage chemotaxis; positive regulation of monocyte chemotaxis; positive regulation of vascular endothelial growth factor production; macrophage chemotaxis; neutrophil chemotaxis; positive chemotaxis
Cellular component: extracellular region
Genetic constraint (gnomAD): Loss-of-function variants: 5 observed, 10.24 expected, observed/expected ratio (o/e) 0.49, 90% interval 0.25 to 1.03. The upper end of that interval is the gene's LOEUF score, 1.03, which puts it in group 4 of 6, group 1 being the genes least tolerant of losing a copy. Missense variants: 111 observed, 121.12 expected, observed/expected ratio (o/e) 0.92, 90% interval 0.79 to 1.07. Synonymous variants: 48 observed, 48.62 expected, observed/expected ratio (o/e) 0.99, 90% interval 0.78 to 1.26.
Homologues: Orthologues: chimpanzee CXCL17 (98% identical), macaque CXCL17 (95% identical), guinea pig CXCL17 (76% identical), rabbit CXCL17 (76% identical), mouse Cxcl17 (71% identical), rat Cxcl17 (61% identical).
Diseases named in the same sentence as CXCL17 in open-access papers:
CXCL17 is named in the same sentence as 73 diseases in open-access papers, as found by Europe PMC text mining. Sharing a sentence is not in itself a finding about the gene and the disease. The quoted sentences say what the papers report.
COVID-19 (13 papers, 2020 to 2025). A disease caused by infection with severe acute respiratory syndrome coronavirus 2. "Furthermore, serum levels of CXCL17 are differentially regulated during influenza and COVID-19, pointing to a possible diagnostic value for the chemokine." (PMID 33717172, 2021). "CCL-19, CCL-22, and CXCL-17 are also frequently raised in acute COVID-19 cases and are involved in T-cell, dendritic cell, and macrophage chemotaxis." (PMID 39000027, 2024). "Other potential mechanisms involved the ribosome and COVID-19 pathways; the inflammatory factors genes, such as Ccl17, Cxcl17, Cd163, Cxcr5, and Il31ra, and the lncRNAs genes; and the respiratory cilia functions." (PMID 36072401, 2022). "Future studies on the role of CXCL17 not only in severe pandemic influenza, but also in seasonal influenza, COVID-19, and PTB are required to validate our results." (PMID 33717172, 2021). "As observed in influenza infected lung sections, the expression of CXCL17 in the lungs of deceased COVID-19 patients was also detected within macrophages and alveolar epithelial cells." (PMID 33717172, 2021). "Together, these data point to a possible role for chemokines involved in the recruitment of myeloid cells to the lungs during COVID-19, and CXCL17 is an excellent candidate to mediate this recruitment." (PMID 33717172, 2021). "We also evaluated the tissue-expression pattern of CXCL17 in lungs of patients that succumbed to COVID-19." (PMID 33717172, 2021). "To further estimate the diagnostic value of CXCL17, we performed a ROC curve analysis with the serum levels of CXCL17 of influenza and COVID-19 subjects." (PMID 33717172, 2021). "Of the anti-inflammatory cytokines, CXCL17 is upregulated in COVID-19 patients as well, but more research must be done to investigate its role in COVID-19 pathogenesis." (PMID 32752138, 2020). "Thus, the chemokine antibody signature that distinguished healthy controls from COVID-19 convalescents (autoantibodies to CCL19, CCL22 and CXCL17) was different from the signature associated with COVID-19 severity (autoantibodies to CXCL5, CXCL8 and CCL25)." (PMID 36879067, 2023). "Other potential mechanisms of the RC decoction against the ALI involved the pathways of ribosome and coronavirus disease 2019 (COVID-19); the target genes of inflammatory factors, such as Ccl17, Cxcl17, Cd163, Cxcr5, and Il31ra, and lncRNAs; and the regulations of the respiratory cilia." (PMID 36072401, 2022). "Whether longitudinal changes in serum CXCL17 levels could have a prognostic value in COVID-19 should be investigated in future studies." (PMID 33717172, 2021). "Although individuals with this disease rarely present with ARDS, the fact that only influenza but not PTB or COVID-19 patients showed high CXCL17 levels remarks the specific diagnostic potential of this chemokine during influenza." (PMID 33717172, 2021). "We observed that CXCL17 levels could reliably differentiate between influenza and COVID-19, with an AUC of 0.81." (PMID 33717172, 2021). "However, we found that the magnitude of CXCL17 expression in the serum was also robust during influenza but minimal in COVID-19 patients." (PMID 33717172, 2021). "Therefore, our immunohistochemical analysis evaluated the expression of CXCL17 only during the latest phases of viral infection, whereas serum chemokine determinations captured early responses against COVID-19 and influenza." (PMID 33717172, 2021). "Also, we measured serum levels of CXCL17 in COVID-19 patients only at the time of hospital admission." (PMID 33717172, 2021). "Antibodies to the three chemokines with P < 10−4 (CCL19, CCL22 and CXCL17) clustered together and by themselves were sufficient to correctly assign healthy controls and COVID-19 convalescents with high accuracy (96.8%), so they were defined as a ‘COVID-19 signature’." (PMID 36879067, 2023).
COVID-19 (continued). "The elevated CXCL17 levels observed only in severe influenza patients might indicate that they have more regulatory mechanisms to minimize tissue damage than individuals with COVID-19." (PMID 35674675, 2022). "Moreover, CXCL17, a macrophage chemoattractant, is among the chemokines that were firstly upregulated in all SARS-CoV-2 patients whose BALFs were analyzed for meta-transcriptome sequencing, and functional analysis suggests an important role of CXCL17 in COVID-19 pathogenesis." (PMID 35062368, 2022). "Additionally, the expression of CXCL17 was tested in lung autopsy specimens from COVID-19 patients." (PMID 33717172, 2021). "The role of innate immune cells responding to CXCL17 in COVID-19 is unknown, but recent studies have found that the numbers of circulating DCs and monocytes are reduced in patients with severe SARS-CoV-2 infection as compared to patients with milder forms of the disease." (PMID 33717172, 2021). "Also, future studies on the role of CXCL17 in COVID-19 and PTB are warranted." (PMID 33717172, 2021). "Notably, we also demonstrated that these differences could be harnessed for clinical applications, as serum CXCL17 levels determined at hospital admission are useful to distinguish between influenza and COVID-19 in patients with ARDS." (PMID 33717172, 2021). "CCL-22 and CXCL-17, which are often raised alongside CCL-19 in COVID-19, showed little difference between the two arms." (PMID 39000027, 2024). "The main inflammatory cytokines and chemokines widely produced by patients with severe forms of COVID-19 are IL-6, IL-8, IL-1β, TNF-alpha, IFN-gamma, MIP1α and 1β, CCL2, CCL5, CCL20, CXCL1, CXCL2, CXCL8, CXCL10, and CXCL17." (PMID 39768136, 2024). "For instance, severe influenza differs from COVID-19 by higher levels of IL-2, APRIL, sTNF-R1, sTNF-R2, SP-D, and CXCL17." (PMID 35674675, 2022). "CXCL17 was detected in post-mortem lung specimens from patients that died of pandemic influenza A(H1N1) and COVID-19." (PMID 33717172, 2021). "Here, we demonstrate that CXCL17 can be detected in post-mortem human lung specimens from patients with pandemic influenza A(H1N1) and COVID-19." (PMID 33717172, 2021). "However, whether CXCL17 plays a pathogenic or protective role during influenza or COVID-19 is not apparent from our data." (PMID 33717172, 2021). "Conversely, and regardless of vaccination status, antibodies to CCL19, CCL8, CCL13, CCL16, CXCL7 and CX3CL1 significantly increased, those to CXCL17 remained generally stable and those to CCL22 followed variable kinetics at month 12 compared with month 6 in the COVID-19 convalescents." (PMID 36879067, 2023). "However, our observations on TLR5, CXCL17, CCL26, IL1RL2, and IL3RA provide clear proteins to explore to explain sex differences in COVID-19 outcomes." (PMID 36171541, 2022). "Our results indicate that CXCL17 levels were significatively elevated in the serum of influenza cases, but not in healthy donors (HD) or COVID-19 subjects." (PMID 33717172, 2021). "Our results for the first time demonstrate an induction of CXCL17 specifically during pandemic influenza A(H1N1), but not COVID-19 and PTB in humans." (PMID 33717172, 2021). "Furthermore, we found higher serum levels of the C-X-C motif chemokine ligand 17 (CXCL17), a mucosal chemokine with anti-inflammatory properties, in pandemic influenza A(H1N1) but not COVID-19 patients." (PMID 33995342, 2021). "Interestingly, serum levels of CXCL17 were increased only in patients with pandemic influenza A(H1N1), but not COVID-19 and PTB." (PMID 33717172, 2021).
breast carcinoma (12 papers, 2012 to 2025). "According to studies on CXCL17 gene expression in breast cancer, a high level of CXCL17 gene expression in patients is associated with a worse overall survival." (PMID 38384293, 2024). "We also assessed the association between CXCL17 expression and metastasis in breast cancer via the online databases SurvExpress and KM plotter (PMID: 24066126 and PMID: 20020197)." (PMID 30755260, 2019). "Herein, we describe the pathogenic role of CXCL17 in the formation of a lung metastatic niche in the case of breast cancer." (PMID 30755260, 2019). "CXCL17 is significantly upregulated in breast carcinoma and colon tumors and is associated with carcinogenesis, tumor proliferation, and angiogenesis." (PMID 25303284, 2014). "The results suggest that CXCL17 might be associated with metastasis in breast cancer." (PMID 30755260, 2019). "CXCL17-derived CD11b+Gr-1+ myeloid-derived suppressor cells contributed to lung metastasis of breast cancer through platelet-derived growth factor-BB." (PMID 38232115, 2024). "MDSCs derived by C-X-C Motif Chemokine Ligand 17 (CXCL17) enhances the metastatic potential of breast cancer cells through platelet-derived growth factor (PDGF)." (PMID 32595638, 2020). "Our findings identify primary breast cancer-secreted CXCL17 as an important contributor that drives the formation of the lung metastatic niche." (PMID 30755260, 2019). "Next, we determined if CXCL17 would also facilitate breast cancer cell extravasation and long-term lung colonization." (PMID 30755260, 2019). "Here, we demonstrate that breast cancer cells secrete CXCL17, which increases the accumulation of CD11b+Gr-1+ MDSCs in the lungs." (PMID 30755260, 2019). "CXCL17 was expressed most frequently in colon and breast carcinoma cell lines, some gastric cell lines, and non-small cell lung cancer and pancreatic carcinoma cell lines, but not in melanoma cell lines." (PMID 22952881, 2012). "In addition, the administration of CXCL17 is favored for metastasis of breast cancer, whereas knockdown of CXCL17 prevents spontaneous spreading of breast cancer from primary site." (PMID 30755260, 2019). "Our study reveals that MDSCs derived by CXCL17 contribute to the establishment of a lung metastatic niche by PDGF-BB secretion and provide a rationale for development of CXCL17 or PDGF-BB antagonists to inhibit or prevent lung metastasis in cases of breast cancer." (PMID 30755260, 2019). "Given the prominent role of CD11b+Gr-1+ MDSCs in breast cancer metastasizing to the lungs, we next examined whether depletion of CD11b+Gr-1+ MDSCs could decrease lung metastasis of breast cancer induced by CXCL17." (PMID 30755260, 2019). "In addition, CXCL17 levels have been correlated with breast cancer metastases among patients with breast cancer." (PMID 30755260, 2019). "The models including 4T1 and MDA-MB-231 breast cancer used in our study are triple-negative breast cancer; therefore, further study is required to clarify possible roles of ER, PR, or Her2/neu in the regulation of CXCL17 in breast cancer." (PMID 30755260, 2019). "Consequently, both CD11b+Gr-1+ MDSC depletion and PDGF receptor inhibitor effectively prevents CXCL17-driven lung metastasis in breast cancer." (PMID 30755260, 2019). "In breast cancer and colon tumor, CXCL17 is coregulated with vascular endothelial growth factor (VEGF) and it increases vasculature in vivo, suggesting that it might promote tumor progression by enhancing angiogenesis." (PMID 25303284, 2014). "Also, CXCL17 is expressed in some aggressive types of gastrointestinal, lung and breast cancer cells." (PMID 24978043, 2014). "Moreover, preliminary immunohistochemical analyses showed that CXCL17 was positive in some clinical specimens (50% in colorectal cancer, 60% in breast cancer, and 30% in non-small cell lung carcinoma)." (PMID 22952881, 2012). "Therefore, CXCL17 could be used as a prognostic tool as well as a therapeutic target in lung metastasis of breast cancer." (PMID 30755260, 2019).
breast carcinoma (continued). "For a lung metastasis model of breast cancer, researchers have found that breast cancer cells promote GPR35+MDSC colonization in the lung by secreting CXCL17 and G-CSF." (PMID 34689842, 2021). "Chemokine (C-X-C motif) ligand 17 (CXCL17) is a novel 119 amino acid CXC chemokine, which has been reported to express in colon and breast cancers and promotes cancer progression." (PMID 30755260, 2019). "To assess whether CXCL17 promotes lung metastasis through metastatic niche establishment, we treated mice with rm (recombinant mouse protein) CXCL17 via intra-tracheal administration and then implanted breast cancer cells by orthotropic graft or tail vein injection." (PMID 30755260, 2019). "However, CXCL17 did not change cell proliferation, colony formation, and migration of 4T1 breast cancer cells in vitro." (PMID 30755260, 2019). "CXCL17 increases CD11b+Gr-1+ MDSCs to express PDGF-BB, which not only contributes to CD11b+Gr-1+ MDSC-mediated angiogenesis in the lung metastatic niche, but is also involved in the colonization of breast cancer." (PMID 30755260, 2019).
colon cancer (10 papers, 2012 to 2026). "Although CXCL17 expression could not increase the number of CD11b+Gr1+ cells in tumor-burdened SCID mice or promote metastases of low metastatic colon cancer cells, the existence of CXCL17-responding myeloid-derived cells caused a striking enhancement of xenograft tumor formation." (PMID 22952881, 2012). "As an acknowledged inflammatory cytokine, CXCL17 is also participated in various malignancies, including pancreatic ductal adenocarcinoma, lung cancer, colon cancer, and thyroid carcinoma." (PMID 41496085, 2026). "Breast and colon cancers express CXCL17 at significantly higher levels, where it promotes angiogenesis, the spread of cancerous cells, and the development of the disease." (PMID 38384293, 2024). "Several chemokines such as CXCL1, CXCL12, and CXCL2 as well as CXCL17 were involved in the development, growth, and progression of the colon cancer." (PMID 35607443, 2022). "There has been increasing evidence that CXCL17 enhances tumor formation in several carcinomas such as lung metastasis, hepatocellular carcinoma, and colon cancer." (PMID 33670758, 2021). "For CXCL17, it is reported that overexpression of CXCL17 has a strong connection with colon cancer and hepatocellular carcinoma." (PMID 28232943, 2017). "CXCL17 overexpression increased the number of CD11b+/Gr-1+ myeloid-derived cells in colon tumor and was accompanied by enhanced tumorigenicity, implying that CXCL17 plays a tumor-promoting role by regulating immune cell recruitment." (PMID 25303284, 2014). "Interestingly, the myeloid biomarker G-protein-coupled-receptor EMR1 was also ectopically expressed in colon cancer correlating with CXCL17, mainly detecting the same tumor cells." (PMID 35008827, 2021). "Correlations between levels of PRSS3 and PRSS22 mRNAs and CEA, CXCL16, CXCL17, GPR35 V2/3, LGR5, LGR6 and KLK6 mRNA levels in lymph nodes of colon cancer patients." (PMID 40909962, 2025). "Recently, we discovered that chemokines CXCL17 and CXCL16 are ectopically expressed in colon cancer (CC) and could serve as biomarkers for poor prognosis." (PMID 35008827, 2021). "With regard to tumor formation, we found accumulations of immature myeloid cells in the tumor edge of CXCL17-positive colon cancer cell lines, but not CXCL17-negative cell lines." (PMID 22952881, 2012). "We previously studied mRNA biomarkers that correlated with poor prognosis in colon cancer (CC) patients, such as leucine-rich repeat-containing G protein-coupled receptors 5 and 6 (LGR5 and LGR6), as well as C-X-C motif chemokine ligands 16 and 17 (CXCL16 and CXCL17)." (PMID 40909962, 2025). "We further investigated whether CXCL17 expression could induce rapid tumor growth of CXCL17-negative DLD-1 colon cancer cells in SCID mice." (PMID 22952881, 2012).
lung carcinoma (9 papers, 2012 to 2026). "CXCL17 was preferentially expressed in some aggressive types of gastrointestinal, breast, and lung cancer cells." (PMID 22952881, 2012). "Our research shows that CXCL17 stimulates lung cancer tumor growth and spread." (PMID 38384293, 2024). "However, our research is the first to demonstrate that the overexpression of CXCL17 encourages the A549 lung cancer cells to migrate and invade." (PMID 38384293, 2024). "Similarly, this DCB subtype specificity also extends to lung cancer: 4 of the 6 lung DCB genes (CXCL17, SFTA3, SFTPA2, and SLC34A2) were upregulated in the plasma of patients with lung adenocarcinoma compared to those with squamous cell carcinoma." (PMID 33883548, 2021). "While upregulation of CEACAM5 and CXCL17 seems to have a biological explanation, the underlying mechanism of the lower systemic levels of both important cancer related receptor tyrosine kinases, VEGFR2 and ERBB3, in lung cancer patients, remains elusive." (PMID 31357969, 2019). "Again, many of the immune-modulatory genes differentially expressed in the mouse model were site-specifically recapitulated, e.g., higher CCL2, CXCL5, CXCL9, CXCL11, CXCL14, CXCL17, and IDO1 in lung cancers and higher CXCL12, FGL1, and LAG3 in liver cancers." (PMID 33985562, 2021). "However, seven genes selected from FSL (FOXA2, C4BPA, SCGB3A1, DDX58, CCNDBP, TMSB4X, and CXCL17), and one gene selected from both FSL as well as RSL (CD9), were up-regulated in the lung cancer tissues, but not significantly (P > 0.05)." (PMID 23374247, 2013).